KCTD15 (potassium channel tetramerization domain containing 15)
Description:
During embryonic development, it is involved in neural crest formation (By similarity). Inhibits AP2 transcriptional activity by interaction with its activation domain.
Synonyms: MGC25497
Tractability: No criterion of Open Targets' tractability assessment is met for any kind of drug.
Gene: Protein-coding gene on chromosome 19 (33,795,933 to 33,815,763, forward strand). Ensembl gene ENSG00000153885.
Subcellular location: Nucleus
Subcellular location (Human Protein Atlas): Nucleoplasm; Cytosol
Pathways (Reactome):
Gene expression (Transcription): Negative regulation of activity of TFAP2 (AP-2) family transcription factors
Gene Ontology:
Molecular function: identical protein binding; protein binding; transcription corepressor activity
Biological process: negative regulation of DNA-templated transcription; protein homooligomerization
Cellular component: nucleus
Genetic constraint (gnomAD): Loss-of-function variants: 11 observed, 26.75 expected, observed/expected ratio (o/e) 0.41, 90% interval 0.26 to 0.68. The upper end of that interval is the gene's LOEUF score, 0.68, which puts it in group 2 of 6, group 1 being the genes least tolerant of losing a copy. Missense variants: 350 observed, 399.61 expected, observed/expected ratio (o/e) 0.88, 90% interval 0.8 to 0.96. Synonymous variants: 163 observed, 173.99 expected, observed/expected ratio (o/e) 0.94, 90% interval 0.82 to 1.07.
Homologues: Orthologues: guinea pig KCTD15 (99% identical), pig KCTD15 (99% identical), rat Kctd15 (98% identical), mouse Kctd15 (98% identical), rabbit KCTD15 (93% identical), dog KCTD15 (81% identical), zebrafish kctd15a (80% identical), zebrafish KCTD15 (47% identical), Drosophila melanogaster twz (46% identical), Caenorhabditis elegans F32B4.5 (14% identical). Paralogues in human: KCTD1 (76% identical), KCTD19 (28% identical), KCTD8 (26% identical), KCTD6 (24% identical), KCTD12 (24% identical), KCTD16 (23% identical), KCTD21 (23% identical), KCTD7 (23% identical), KCNRG (22% identical), KCTD11 (20% identical), KCTD4 (19% identical), KCTD18 (18% identical), and 1 more.
Diseases named in the same sentence as KCTD15 in open-access papers:
KCTD15 is named in the same sentence as 29 diseases in open-access papers, as found by Europe PMC text mining. Sharing a sentence is not in itself a finding about the gene and the disease. The quoted sentences say what the papers report.
Obesity (39 papers, 2010 to 2024). Accumulation of substantial excess body fat. "Autism and schizophrenia have been associated with KCTD13 deletions, and obesity was associated with KCTD15 variants." (PMID 39202342, 2024). "The gene KCTD15 rs29941 has been previously associated with the risk of obesity, fasting glucose, insulin resistance, and T2D." (PMID 36555722, 2022). "The genetic interaction between TFAP2Β and KCTD15, an obesity-linked gene, is also likely to positively contribute to AP-2β-induced obesity and metabolic dysfunction." (PMID 36076256, 2022). "Genome-wide association studies (GWAS) have identified KCTD15 (potassium channel tetramerization domain containing 15) variants as being associated with increased risk of obesity." (PMID 33805313, 2021). "Particularly, the Kctd15 likely acts through interaction with adipocyte protein 2 (AP-2), which is a critical regulator in adipogenesis, suggesting a possible molecular basis for the observed associations of KCTD15 variants with obesity." (PMID 33193685, 2020). "The locus near rs2012033 was associated in both primary caries GWASs (dft p-value 8.21 × 10− 7; dfs p-value 1.40 × 10− 6) and harbored a candidate gene for hypodontia (CHST8) and a gene associated with obesity and preference for carbohydrate (KCTD15)." (PMID 31533690, 2019). "In this regard, several loci in or near KCTD15 have repeatedly been associated with obesity in a number of GWAS and replication studies." (PMID 28948079, 2017). "The human genes TFAP2B (encoding AP-2β) and KCTD15 were strongly linked to obesity in multiple genome-wide association studies (GWAS), though it is still not understood how they regulate obesity." (PMID 25187989, 2014). "Potassium-channel-tetramerization-domain-containing protein 15 (KCTD15), a member of the K+-channel-tetramerization-domain family, is an obesity-linked protein in humans and is implicated in the crucial physio-pathological processes that are involved in food uptake." (PMID 36978600, 2023). "Variants of the KCTD15 were associated with risk for obesity." (PMID 29966015, 2018). "As to KCTD15, genome wide association studies (GWAS) have indicated a connection to obesity." (PMID 24086424, 2013). "Moreover, KCTD15 is implicated in medulloblastoma, obesity, and diabetes." (PMID 34521919, 2021). "By extending these considerations, it also possible to make a tentative but intriguing functional link between KCTD15 and obesity whose connection has been found at the genetic level." (PMID 34521919, 2021). "Like other KCTD proteins, KCTD15 is involved in important albeit distinct biological processes as cancer, neural crest formation, and obesity." (PMID 34521919, 2021). "Although the role of KCTD15 is unclear in liver diseases, this gene is an obesity-related gene, and its genetic variation (rs29941) was significantly associated with weight changes and fasting plasma glucose level." (PMID 34635168, 2021). "Although the detailed molecular mechanisms are not known, several lines of evidence suggest a potential role for KCTD15 in obesity, through inhibition of Wnt signaling." (PMID 33805313, 2021). "KCTD15 is associated with TFAP2B, and both of them genes have been linked to obesity in GWASs, indicating a possible physical interaction in vivo." (PMID 31341224, 2019). "Varying levels of evidence support their roles in neurocognitive disorders (KCTD3), neurodevelopmental disease (KCTD7), bipolar disorder (KCTD12), autism and schizophrenia (KCTD13), movement disorders (KCTD17), cancer (KCTD11), and obesity (KCTD15)." (PMID 31197948, 2019). "In adipose tissues of 2 obesity mice models, KCTD15 exhibited concomitant obesity-dependent alterations in DNA methylation and gene expression." (PMID 29966015, 2018). "Genome wide association studies (GWAS) in humans have found significant linkage between KCTD15 and obesity." (PMID 29216270, 2017).
Obesity (continued). "Two genes recently associated with obesity have been TFAP2B and KCTD15, for which a combined function that affects eating behavior has been described." (PMID 28948079, 2017). "Further, Tfap2b was also affected by the high-fat diet with up-regulated relative expression levels at 4.78 (SD ±0.67, P>0.01), while Kctd15 was unaffected by obesity (0.99±0.09 (±SD)." (PMID 25187989, 2014). "A recent review suggests that KCTD15 affects obesity through regulation of AP-2, mediated by SUMOylation." (PMID 24086424, 2013). "Other loci, including the INSIG2, TMEM18, KCTD15, SH2B1, MTCH2, GNPDA2, BDNF, or CHST8 genes, have also been associated with obesity." (PMID 24267414, 2013). "The obesity-risk-allele score based on genotypes at eight SNPs associated with childhood BMI (in/near to: FTO, MC4R, TMEM18, GNPDA2, NEGR, KCTD15, BDNF, and ETV5) ranged from 2 to 15 alleles." (PMID 20520848, 2010). "The observed upregulation of IKK-β by KCTD15 provides a novel and intriguing interpretative key for understanding the protein function in a wide class of physiological/pathological conditions ranging from neuronal development to cancer and obesity/diabetes." (PMID 34521919, 2021). "KCTD15 overexpression has never been reported to be linked to pathological states, although it has been indirectly associated with obesity in several literature reports and numerous studies showed an association between this gene and obesity." (PMID 31882877, 2019). "The SNP rs11084753, mapped downstream of the KCTD15 gene, was previously linked to BMI with the G allele increasing the risk of obesity in nonpregnant individuals." (PMID 29686896, 2018). "TFAP2B and KCTD15 are obesity‐related genes that interact to regulate feeding behavior." (PMID 28948079, 2017). "The analysis of obese patients in our sample could confirm that KCTD15 and TFAP2B variants may be related to obesity risk, a finding that has also been suggested by a number of GWAS and replication studies." (PMID 28948079, 2017). "Our study describes how the obesity-linked homologues TfAP-2 (human TFAP2B) and Tiwaz (human KCTD15) regulate a unique feedback system involving noradrenalin-like octopamine and the CCK homolog Dsk, that exert positive and negative effects on Drosophila feeding behavior." (PMID 25187989, 2014). "In conclusion, our data suggests that the human obesity-linked genes TFAP2B and KCTD15 could directly interact in regions of the brain known to regulate feeding behavior." (PMID 25187989, 2014). "Apart from those in FTO, several of the identified SNPs are located in or near genes clearly related to appetite regulation, and recently, five of the novel obesity loci (SH2B1, KCTD15, MTCH2, NEGR1 and BDNF) were indicated to be associated with dietary macronutrient intake levels." (PMID 23861046, 2013). "SNPs in SH2B1, SFRS10 and KCTD15 associated with increased risk of overweight, but not with obesity, while the risk alleles in MC4R and NEGR1 associated with increased risk of obesity, but not with overweight." (PMID 23861046, 2013). "Finally, the observed upregulation of IKK-β by KCTD15 provides a novel and intriguing interpretative key for understanding a wide and diversified class of physiological and pathological states ranging from neuronal development to obesity and diabetes." (PMID 34521919, 2021). "For three types of cancer (LUSC, BLCA, and LUAD), history of smoking and expression levels of three obesity-related genes (SH2B1, POMC, and KCTD15) influenced the survival probability of patients with LUSC." (PMID 33299884, 2020). "The expression level of each of the five obesity-related genes (SH2B1, GNPDA2, FTO, TMEM18, and KCTD15) in three cancer tissues (HNSC, LIHC, and CHOL) was higher than that in the corresponding normal tissues." (PMID 33299884, 2020).
Obesity (continued). "The expression levels of other eight obesity-related genes (TMEM18, KCTD15, GNPDA2, SH2B1, FTO, LEP, PCSK1, and GPR120) in about half types of cancer tissues were higher/lower than those in the corresponding normal tissues." (PMID 33299884, 2020). "Despite a lack of extensive research on the KCTD15 gene, studies with animal models have indicated a relationship between this gene and obesity-related behaviors." (PMID 29686896, 2018).
breast carcinoma (6 papers, 2021 to 2024). "On the other hand, a strong intensity of the signal (score 3) is associated with HER2+ breast cancer (third lane) and with the positive control, i.e., IHC of anti KCTD15 antibody (Spleen tissue)." (PMID 35328144, 2022). "Using the CRISPR/CAS9 protocol that we recently developed for knocking down the related protein, KCTD15, in breast cancer cells showed that the KCTD1 gene was downregulated in SW480 cells." (PMID 36979172, 2023). "A cytofluorimetric analysis of KCTD15 expression clearly indicates that breast cancer cell lines present significantly higher KCTD15 expression compared to MCF10A." (PMID 35328144, 2022). "The analysis of the KCTD15 levels indicates a significant overexpression of the protein in Luminal A and Luminal B breast cancer patients as well as in the related cell lines." (PMID 35328144, 2022). "A connection between the KCTD15 and the NF-κB pathway has also been detected in the breast cancer cell line SKBR3." (PMID 35328144, 2022). "Collectively, the data presented suggest that KCTD15 play an active role in the insurgence of specific cases of breast cancer and open new opportunities in the diagnosis and therapy of this this highly heterogeneous disease." (PMID 35328144, 2022). "An extension of these results was achieved by silencing KCTD15 in breast cancer cell line (SKBR3), where this protein is remarkably upregulated." (PMID 34521919, 2021). "KCTD15 was recently shown to be overexpressed in human childhood leukaemia and breast cancer." (PMID 36979172, 2023). "Moreover, we also examined overall survival (OS) in breast cancer patients who received treatment, either chemical or hormonal, using the Kaplan–Meier plot as a function of KCTD15 expression levels." (PMID 35328144, 2022).
leukemia (6 papers, 2019 to 2024). A malignant (clonal) hematologic disorder, involving hematopoietic stem cells and characterized by the presence of primitive or atypical myeloid or lymphoid cells in the bone marrow and the blood. "Very recently, it has been reported that KCTD15, a protein typically associated with other physio-pathological processes, is involved in medulloblastoma and leukemia." (PMID 35328144, 2022). "The silencing of KCTD15 in MLL-rearranged leukemia models induced attenuation of the NF-κB pathway associated with a downregulation of pIKK-β and pIKB-α." (PMID 34521919, 2021). "Interestingly, as for leukemia cell lines, this KCTD15 inactivation caused a decrease of the expression levels of both pIKB-α and pIKK-β compared to the controls." (PMID 34521919, 2021). "This is the first time that KCTD15 has been associated with leukemia pathogenesis." (PMID 31882877, 2019). "On the other hand, the transcriptomic analysis of T-ALL patients highlighted KCTD1, KCTD9, KCTD11, and KCTD15 to be upregulated in pediatric leukemia patients." (PMID 37297863, 2023). "In a first instance, the transient silencing of KCTD15 in MLL-rearranged leukemia model systems (RS4;11 and SEM) induced cell death and apoptosis with a significant downregulation of pIKK-β, the kinase deputed to the activation of the NF-κB pathway." (PMID 34521919, 2021). "Here, we extend our investigation by monitoring the KCTD15 expression levels in circulating lymphocytes, monocytes, and granulocytes, as well as in leukemia cells." (PMID 32512747, 2020). "Collectively, data here presented indicate that KCTD15 is an important and hitherto unidentified player in this kind of childhood leukemia." (PMID 31882877, 2019). "In addition to the role that KCTD15 plays in leukemia and the maturation of blood cells, previous studies have demonstrated this protein inhibits neural crest formation by attenuating Wnt/beta-catenin pathway." (PMID 34521919, 2021). "In the present manuscript, starting from the analysis of the transcriptome of the peripheral blood of healthy individuals and leukemia patients, we highlighted the possibility that KCTD15 could be involved in the NF-κB signaling." (PMID 34521919, 2021). "The ability of KCTD15, emerged from the present analyses, play a role in the NF-κB pathway in both pathological and physiological contexts holds interesting implications on the etiology of leukemia that could also apply to other carcinogenic processes." (PMID 34521919, 2021). "Collectively, data here presented indicate that KCTD15 is an important and hitherto unidentified player in childhood lymphoid leukemia, and its study could open a new scenario for the identification of altered and still unknown molecular pathways in leukemia." (PMID 31882877, 2019). "Not only do the present findings provide a mechanism for interpreting the role of the protein in leukemia and the physiological T-cells but they provide a novel perspective for interpreting the role of KCTD1/KCTD15 in other, apparently distant, processes." (PMID 34521919, 2021).
medulloblastoma (6 papers, 2019 to 2024). A malignant, invasive embryonal neoplasm arising from the cerebellum. "Natural mutants of KCTD1 have been demonstrated to be the causative agents of the scalp-ear-nipple syndrome whereas KCTD15 inhibits the Hedgehog pathway in medulloblastoma cells." (PMID 35328144, 2022). "Indeed, these results, although suggestive, indicate that only a subpopulation of SHH medulloblastoma expresses significantly low KCTD15 mRNA levels." (PMID 31685809, 2019). "However, KCTD15 functions differently in medulloblastoma cells." (PMID 38438714, 2024). "KCTD15 inhibits the Hedgehog signaling pathway by increasing the stability of the tumor suppressor KCASH2, thereby inhibiting the proliferation of medulloblastoma cells." (PMID 35705627, 2022).
acute lymphoblastic leukemia (2 papers, 2019 to 2020). Leukemia with an acute onset, characterized by the presence of lymphoblasts in the bone marrow and the peripheral blood. "Recently, we identified KCTD15 as a novel player involved in the pathophysiology of pediatric acute lymphoid leukemias." (PMID 32512747, 2020).
acute myeloid leukemia (2 papers, 2020 to 2021). Acute myeloid leukemia (AML) is a group of neoplasms arising from precursor cells committed to the myeloid cell-line differentiation. "Here, we decided to better describe the pattern of KCTD15 expression in peripheral blood cells as well as in acute myeloid leukemia cell lines and samples." (PMID 32512747, 2020). "In this scenario, using a multiparametric flow cytometry approach, we here evaluate KCTD15 expression levels in circulating lymphocytes, monocytes, and granulocytes, as well as in human acute myeloid leukemia-derived cell lines." (PMID 32512747, 2020). "This in vitro finding was corroborated by the analysis of KCTD15 mRNA of acute myeloid leukemia (AML) patients reported in the Microarray Innovations in Leukemia (MILE) dataset." (PMID 32512747, 2020). "On the other hand, Smaldone and colleagues have shown that KCTD15 is upregulated in B-cell type acute lymphoblastic leukemia (B-ALL) patients and acute myeloid leukemia (AML) patients." (PMID 34001146, 2021). "The analysis reported in the previous paragraph and our previous observation of the upregulation of KCTD15 in ALL cell lines and patients prompted us to evaluate the expression levels of the protein in acute myeloid leukemia (AML)-derived cell lines." (PMID 32512747, 2020).
colorectal cancer (2 papers, 2023 to 2024). A primary or metastatic malignant neoplasm that affects the colon or rectum. "Potassium Channel Tetramerization Domain Containing 15 (KCTD15) participates in the carcinogenesis of several solid malignancies; however, its role in colorectal cancer (CRC) remains unclear." (PMID 38438714, 2024). "Interestingly, the evaluation of the expression levels of KCTD12 and KCTD15—which are related to KCTD1—in colorectal cancer using TCGA data highlights similar downregulation." (PMID 36979172, 2023).
anorexia nervosa (1 paper, 2017). A disorder most often seen in adolescent females characterized by a refusal to maintain a minimally normal body weight, an intense fear of gaining weight, a disturbance in body image, and, in postmenarcheal females, the development of amenorrhea. "According to this background, we hypothesized in the present work that TFAP2B and KCTD15 variants, either isolated or in combination, may influence personality dimensions in anorexia nervosa (AN) or bulimia nervosa (BN) patients." (PMID 28948079, 2017). "Haplotype *6 in KCTD15 was more frequent in controls (OR = 0.40 [0.20–0.80], p = .009 for anorexia nervosa), while haplotype *4 in TFAP2B affected all three scales of the SCL‐90R inventory in BN patients (p ≤ .01)." (PMID 28948079, 2017).
bulimia nervosa (1 paper, 2017). A disorder characterized by recurrent episodes of binge-eating over which the individual feels a lack of control; these episodes of binge-eating are followed by recurrent compensatory behavior to prevent weight gain, usually self-induced vomiting. "The KCTD15 rs287103 T variant allele was associated with increased risk of bulimia nervosa (BN) (OR = 4.34 [1.47–29.52]; p = .003) and with scores of psychopathological scales of these patients." (PMID 28948079, 2017).